FOXA3 (forkhead box A3)
Description:
Transcription factor that is thought to act as a 'pioneer' factor opening the compacted chromatin for other proteins through interactions with nucleosomal core histones and thereby replacing linker histones at target enhancer and/or promoter sites (By similarity). Originally described as a transcription activator for a number of liver genes such as AFP, albumin, tyrosine aminotransferase, PEPCK, etc. Interacts with the cis-acting regulatory regions of these genes. Involved in glucose homeostasis; binds to and activates transcription from the G6PC1 promoter. Binds to the CYP3A4 promoter and activates its transcription in cooperation with CEBPA. Binds to the CYP3A7 promoter together with members of the CTF/NF-I family. Involved in regulation of neuronal-specific transcription. May be involved in regulation of spermatogenesis.
Synonyms: HNF3G; TCF3G; FKHH3
Tractability: No criterion of Open Targets' tractability assessment is met for any kind of drug.
Gene: Protein-coding gene on chromosome 19 (45,863,989 to 45,873,798, forward strand). Ensembl gene ENSG00000170608.
Subcellular location: Nucleus
Subcellular location (Human Protein Atlas): Nucleoplasm
Pathways (Reactome):
Developmental Biology: Regulation of gene expression in beta cells
Gene Ontology:
Molecular function: DNA-binding transcription factor activity; protein binding; sequence-specific double-stranded DNA binding; transcription cis-regulatory region binding; DNA-binding transcription factor activity, RNA polymerase II-specific; RNA polymerase II cis-regulatory region sequence-specific DNA binding; DNA binding; protein domain specific binding; sequence-specific DNA binding
Biological process: positive regulation of transcription by RNA polymerase II; anatomical structure morphogenesis; cell differentiation; intracellular glucose homeostasis; regulation of transcription by RNA polymerase II; regulation of DNA-templated transcription; spermatogenesis
Cellular component: nucleoplasm; chromatin; nucleus
Genetic constraint (gnomAD): Loss-of-function variants: 11 observed, 17.37 expected, observed/expected ratio (o/e) 0.63, 90% interval 0.4 to 1.05. The upper end of that interval is the gene's LOEUF score, 1.05, which puts it in group 4 of 6, group 1 being the genes least tolerant of losing a copy. Missense variants: 423 observed, 467.25 expected, observed/expected ratio (o/e) 0.91, 90% interval 0.83 to 0.98. Synonymous variants: 217 observed, 203.81 expected, observed/expected ratio (o/e) 1.06, 90% interval 0.95 to 1.19.
Homologues: Orthologues: chimpanzee FOXA3 (100% identical), macaque FOXA3 (99% identical), dog FOXA3 (93% identical), guinea pig FOXA3 (93% identical), pig FOXA3 (92% identical), mouse Foxa3 (89% identical), rat Foxa3 (81% identical), rabbit FOXA3 (50% identical). Paralogues in human: FOXA1 (52% identical), FOXA2 (50% identical), FOXC2 (28% identical), FOXC1 (27% identical), FOXD2 (27% identical), FOXD1 (26% identical), FOXB1 (25% identical), FOXD4L1 (25% identical), FOXD3 (25% identical), FOXD4 (25% identical), FOXD4L3 (25% identical), FOXD4L4 (25% identical), and 29 more.
Diseases named in the same sentence as FOXA3 in open-access papers:
FOXA3 is named in the same sentence as 59 diseases in open-access papers, as found by Europe PMC text mining. Sharing a sentence is not in itself a finding about the gene and the disease. The quoted sentences say what the papers report.
hepatocellular carcinoma (18 papers, 2010 to 2026). A malignant tumor that arises from hepatocytes. "FOXA3 methylation has been found to cause dedifferentiation and sorafenib resistance in hepatocellular carcinoma." (PMID 41140666, 2025). "FOXA3 has been reported to act as a cancer promoter or anti-cancer gene in various malignancies, including hepatocellular carcinoma, cholangiocarcinoma, and esophageal cancer." (PMID 37876483, 2023). "The exogenous expression of HNF4A and FOXA3 in hepatoma cells initiated the endogenous expression of a large number of hepatocyte nuclear factors and promoted the transformation of hepatoma cells into hepatocyte-like cells." (PMID 35132353, 2022). "In other studies, researchers have found that the combination of HNF1A, HNF4A and fork head box protein A3 (FOXA3) can reprogram hepatocellular carcinoma cells into hepatocyte-like cells." (PMID 34234870, 2021). "It's worth noting that the combination of three liver transcriptional factors (TF), HNF1A, HNF4A, and FOXA3 transduced the Hepatocellular carcinoma (HCC) cell lines to more stably suppress cell proliferation." (PMID 34234870, 2021). "It has been found that the simultaneous expression of HNF1α, HNF4α and FOXA3 can transform hepatoma cells into hepatocyte-like cells." (PMID 35096588, 2021). "Transfections of HNF4A, HNF1A and FoxA3 suppressed hepatocellular carcinoma (HCC) cell proliferation, suggesting tumor suppressive roles of FoxA3 in HCC." (PMID 32151057, 2020). "On the contrary, FOXA3 was reported to inhibit the growth of hepatocellular carcinoma cells in vitro." (PMID 28255028, 2017). "Furthermore, the combined expression of HNF1A, HNF4A, and forkhead box protein A3 (FOXA3) was noted to inhibit hepatocellular carcinoma cell growth." (PMID 41583511, 2026). "Mechanically, the exogenous expression of HNF1α, HNF4α and FOXA3 in hepatocellular carcinoma cells promotes the endogenous expression of a variety of hepatocyte nuclear factors, including C/EBP, thus promoting the transformation of hepatocellular carcinoma cells into hepatocyte-like cells." (PMID 35096588, 2021). "Moreover, enforced expression of Foxa3, together with other factors, promotes differentiation of ESCs into a hepatic lineage, and converts fibroblasts and even hepatoma cells into hepatocytes or hepatocyte-like cell." (PMID 34595169, 2021). "Moreover, we also recently have reported that the combination of HNF1A, HNF4A, and FOXA3 synergistically reprograms the hepatocellular carcinoma (HCC) cells to hepatocyte-like cells." (PMID 34141708, 2021). "Our findings with the human colon cancer cell line Caco-2 agreed well with previous studies on the human hepatoma HepG2 cell line co-transfected with HNF6 or its deletion mutants as well as FOXA1, FOXA2, or FOXA3 TATA-luciferase reporter constructs." (PMID 20967225, 2010). "Interestingly, enforcing expression of HNF4α, in cooperation with Forkhead Box Protein A3 (FOXA3) and Hepatocyte Nuclear Factor 1-Alpha (HNF1α), could even reverse the hepatocellular carcinoma (HCC) cells into normal hepatocyte-like cells." (PMID 36249028, 2022).
asthma (5 papers, 2017 to 2025). "We report airway cis-genetic risk variants for MUC5AC and FOXA3, alleles of which are associated with both increased expression of these genes and asthma risk." (PMID 35347136, 2022). "Thus, our results suggest that the greatest impact of the FOXA3 variant on asthma risk will be among T2-low subjects, where possession of the high expressing genotype can drive FOXA3 expression levels up to a risk-conferring level, already eclipsed among T2-high subjects." (PMID 35347136, 2022). "The top FOXA3 eQTL (rs8103278), where the G allele is associated with increased asthma risk, was highly co-localized (PP4 = 0.97) with the FOXA3 COA GWAS locus (p = 1.1e–63), strengthening confidence that rs8103278 enhances asthma risk by upregulating this gene." (PMID 35347136, 2022). "We next examined whether asthma frequency differed among children in the six strata of FOXA3 expression created by the intersection of eQTL genotype and T2 status." (PMID 35347136, 2022). "Thus, it is significant that we report here for the first time an airway eQTL for FOXA3 that confers risk of asthma, which was identified in our nasal TWAS, but not the parent GWAS analysis." (PMID 35347136, 2022). "In addition to FOXA3, we identified eight other COA and three other AOA genes, not within significant GWAS loci, revealing additional aspects of genetically-driven asthma pathobiology." (PMID 35347136, 2022). "In an ovalbumin (OVA)-induced asthma model, conditional deletion of Mpc2-but not Ldha-in club cells impaired club-to-goblet cell differentiation, reduced CLCA3 and Foxa3 expression, and attenuated eosinophilic inflammation and Il-13 expression." (PMID 41418787, 2025).
diabetes (5 papers, 2009 to 2024). "Moreover, FOXA3 participates on the pathway maturity onset diabetes as well as carbohydrate and glucose homeostasis." (PMID 33531552, 2021). "Among the genes that were significantly up-regulated in diabetes were Retnla, Gjb2, Itga, Slit and Dusp6, and among the genes that were down-regulated were Krueppel-like factor 8, IGFBP, Ngfg, Foxa3, Kcnc2 and Dlp8." (PMID 19649297, 2009). "Forkhead box A3 (FOXA3) belongs to the Forkhead-box (FOX) gene family, the dysregulation of which is responsible for various human diseases such as congenital disorders, diabetes mellitus, and carcinogenesis." (PMID 37876483, 2023). "In addition, genes in the mature onset diabetes in young people (hsa04950) pathway (such as HES1, GCK, FOXA3, MAFA, HNF4A, HHEX, and PDX1) were increased in stages II to IV; these genes are related to insulin secretion and the maturation of pancreatic β-cells." (PMID 33897780, 2021).
Hepatic steatosis (4 papers, 2022 to 2026). Steatosis is a term used to denote lipid accumulation within hepatocytes. "Aging FOXA3 gene deficient mice increased white adipose browning and thermogenesis, reduced adipose tissue expansion, improved hepatic steatosis and insulin sensitivity, and extended lifespan." (PMID 36798663, 2023). "Taken together, these studies indicate that activation of the TGR5 signaling is required for hepatic FOXA3 to ameliorate Western diet–induced obesity and hepatic steatosis." (PMID 38447926, 2024). "Overexpression of hepatic FOXA3 reduced hepatic steatosis in chow-fed mice and attenuated Western diet–induced obesity and steatohepatitis." (PMID 38447926, 2024). "When FOXA3 expression is increased, sterol regulatory element binding protein 1c (SREBP1c) expression is also increased, leading to lipid accumulation and hepatic steatosis, alleviated after FOXA3 knockout." (PMID 36535923, 2022). "Forkhead box protein A3 (FOXA3) is a key transcription factor that regulates liver metabolism; however, its specific role in the pathogenesis of fatty liver in dairy cows remains unclear." (PMID 41745951, 2026). "Hepatic FOXA3 is reduced in obesity and fatty liver disease." (PMID 38447926, 2024). "FOXA3 further upregulated lipid synthesis gene programs through its target PER1, leading to hepatic steatosis." (PMID 36798663, 2023).
liver cancer (4 papers, 2020 to 2025). An epithelial or non-epithelial malignant neoplasm that arises from the liver. "Based on RNA-seq analysis, ectopic expression of FOXA3, HNF1A, and HNF4A resulted in expression levels in iHeps that are comparable to those observed in liver cancer cell lines." (PMID 34302118, 2021).
lung carcinoma (4 papers, 2017 to 2023). "A study also indicates that FOXA3 is deregulated in lung cancer and that high FOXA3 expression is linked to adverse overall survival, suggesting FOXA3 can serve as a prognostic biomarker for lung cancer patients." (PMID 37876483, 2023). "Next, we sought to determine whether FOXA3 or SPDEF recapitulates the in vivo function in human lung cancer cells that harbor a KRAS mutation." (PMID 28255028, 2017). "FOXA3 and SPDEF induce MUC5AC and MUC5B, while HNF4A induces MUC3 in human lung cancer cells harboring a KRAS mutation." (PMID 36860703, 2022). "High expressions of FoxA1 and FoxA3 in lung cancer were related with poor overall survival, whereas FoxA2 overexpression was associated with a better overall survival, suggesting the opposing roles between FoxA1/A3 and FoxA2 in the carcinogenesis." (PMID 32151057, 2020). "These suggested that FoxA3 plays oncogenic function in lung cancer and esophageal cancer via elevation of FoxA1 and FoxA2 expressions." (PMID 32151057, 2020). "High expression of FoxA3 was correlated with poor prognosis in lung cancer." (PMID 32151057, 2020). "Previously, our ChIP‐seq analyses determined that NKX2‐1 and FOXA3 bound to the locus of MUC5AC in A549 lung carcinoma cells and BEAS‐2B transformed bronchial epithelial cells, suggesting that the expression of MUC5AC is directly regulated by NKX2‐1 and FOXA3." (PMID 28255028, 2017).
Obesity (4 papers, 2022 to 2026). Accumulation of substantial excess body fat. "Hepatic FOXA3 is reduced in obesity and patients with metabolic dysfunction-associated steatohepatitis (MASH)." (PMID 41683889, 2026). "In the current study, we investigated the role of overexpression of hepatic FOXA3 in obesity and MASH development and the underlying mechanisms." (PMID 38447926, 2024). "Given the role that FOXA3 plays in macrophage cholesterol efflux and its possible association with insulin resistance, obesity, and atherosclerosis, we consider it interesting to carry out studies on the association of polymorphisms of this gene with cardiovascular diseases and metabolic parameters." (PMID 35625529, 2022). "Our data demonstrate that overexpression of hepatic FOXA3 prevents Western diet–induced obesity and steatohepatitis via activation of TGR5." (PMID 38447926, 2024). "Previous studies show that hepatic FOXA3 is markedly reduced in genetic or high-fat diet–induced obesity and MASH patients." (PMID 38447926, 2024). "To understand how overexpression of hepatic FOXA3 prevented Western diet–induced obesity, we analyzed energy expenditure using Comprehensive Lab Animal Monitoring System." (PMID 38447926, 2024). "In this project, we show that overexpression of hepatic FOXA3 reduces hepatic TG accumulation in chow-fed mice and ameliorates Western diet–induced obesity and MASLD/MASH." (PMID 38447926, 2024). "The beneficial effects of hepatic FOXA3 overexpression on Western diet–induced obesity and steatohepatitis were abolished in Tgr5−/− mice." (PMID 38447926, 2024). "In summary, we have identified a novel role of hepatic FOXA3 in regulating lipid and BA metabolism, obesity, and MASH." (PMID 38447926, 2024). "FOXA3 promotes adipocyte differentiation and has been involved in developing insulin resistance and obesity related with age." (PMID 35625529, 2022). "Since hepatic FOXA3 is markedly reduced in obesity and MASH, targeting hepatic FOXA3 may be a useful strategy for the treatment of obesity and MASH." (PMID 38447926, 2024). "Previous studies have shown that hepatic FOXA3 expression is markedly reduced in obesity or MASH." (PMID 38447926, 2024). "Thus, hepatic FOXA3 overexpression attenuates Western diet–induced obesity via increasing energy expenditure." (PMID 38447926, 2024). "However, the role of hepatic FOXA3 in regulating obesity or steatohepatitis remains to be investigated." (PMID 38447926, 2024). "At the molecular level, transcription control through forkhead box protein A3 (FOXA3) has been proposed as a potential regulatory factor for WAT accretion and BAT decline during aging and obesity." (PMID 36936928, 2023). "FOXA3 also induces FAO and inhibits SREBP2, which, together with reduced obesity, may account for reduced hepatic FFA and FC levels in Western diet–fed mice." (PMID 38447926, 2024). "Our data showed that overexpression of hepatic FOXA3 raised plasma BA levels and attenuated Western diet–induced obesity and MASH in WT mice but not in Tgr5−/− mice." (PMID 38447926, 2024). "Our data show that hepatic FOXA3 improves diet-induced obesity and MASH in WT mice, but not in Tgr5−/− mice, suggesting that activation of TGR5 plays a key role in mediating the beneficial effects of FOXA3." (PMID 38447926, 2024). "However, whether hepatic FOXA3 regulates diet-induced obesity or MASH has not been investigated." (PMID 38447926, 2024).
colon cancer (3 papers, 2010 to 2022). "First, enforced expression of HHEX or Foxa3 individually or in combination in colon cancer cell line HCT116 caused discernible change in cell morphology, as compared with control cells." (PMID 34595169, 2021). "Moreover, relatively high co-expression scores were also observed for RUNX2/ETS1, RUNX2/FOXO3, HNF1B/HNF4A, and HNF1B/FOXA3, suggesting that the DETFs associated with DARs might work together and be responsible for 5-FU resistance in colon cancer cells." (PMID 35252200, 2022). "Combined expression of HHEX and FOXA3 exhibited an inhibitory effect of tumorigenesis in a chemically induced colon cancer model." (PMID 34595169, 2021). "We made the colon cancer model using an established strategy, AAV particles (either control virus or a 1:1 mix of virus for HHEX and Foxa3 expression) were administered twice via enema as indicated." (PMID 34595169, 2021).
Insulin resistance (3 papers, 2022 to 2023). Increased resistance towards insulin, that is, diminished effectiveness of insulin in reducing blood glucose levels. "FOXA3 was directly involved in the development of age-related obesity and insulin resistance, and levels of FOXA3 were significantly and selectively increased in brown and inguinal white fat depots during aging." (PMID 36798663, 2023).
atherosclerosis (2 papers, 2022 to 2026). A disease characterized by the build-up of fatty material and calcium deposition in the arterial wall resulting in partial or complete occlusion of the arterial lumen. "Thus, the present study aimed to establish if the FOXA3 polymorphisms are associated with subclinical atherosclerosis (SA) and cardiometabolic parameters." (PMID 35625529, 2022). "Thus, the present study aimed to evaluate the association of two FOXA3 polymorphisms with subclinical atherosclerosis (SA) and cardiometabolic parameters in a cohort well-characterized from the clinical, tomographic, and biochemical points of view." (PMID 35625529, 2022). "Considering that overexpression of FOXA3 could reduce atherosclerosis, increasing the reverse cholesterol transport, we analyzed the distribution of two FOXA3 polymorphisms in individuals with and without SA." (PMID 35625529, 2022).
breast carcinoma (2 papers, 2019 to 2021). "Studies found that many genes unexpectedly enriched in mucin-producing gastrointestinal, pancreatic, and breast cancer showed significant differences in IMAs, including FOXA3, SPDEF, etc.." (PMID 33568091, 2021). "Here, we show FOXA1 expression in breast cancer metastases, but it is still unclear whether other FOXA family members such as FOXA2 and FOXA3 also play a role in breast cancer." (PMID 30819139, 2019).
cholangiocarcinoma (2 papers, 2020 to 2023). A carcinoma that arises from the intrahepatic biliary tree (intrahepatic cholangiocarcinoma) or from the junction, or adjacent to the junction, of the right and left hepatic ducts (hilar cholangiocarcinoma). "FOXA3 is also revealed to promote the proliferation as well as invasion of cholangiocarcinoma cells." (PMID 37876483, 2023). "The expressions of FoxA2 and FoxA3 in cholangiocarcinoma were at similar levels with those in colon adenocarcinoma, liver hepatocellular carcinoma, pancreatic adenocarcinoma, rectum adenocarcinoma, and stomach adenocarcinoma." (PMID 32151057, 2020).